IL17A (interleukin 17A)
Diseases named in the same sentence as IL17A in open-access papers (continued):
Sharing a sentence is not in itself a finding about the gene and the disease.
asthma (continued). "The expression levels of IL-17A correlated with airway hyperresponsiveness (AHR) and clinical severity, suggesting that IL-17A may contribute to the pathogenesis of a certain type of asthma." (PMID 24454477, 2013). "Finally this study provides informations on ICS and LABA as useful therapeutic strategies to control the Th17 immunity and IL-17A activity in children with moderate forms of asthma and rhinitis." (PMID 23573194, 2013). "In this scenario, IL-17A in allergic rhinitis and asthma may cover both the innate and the adaptive aspects representing the crucial crosstalk between immune system and structural cells such as airway epithelial cells and fibroblasts." (PMID 23573194, 2013). "Finally, Budesonide with Formoterol reduced IL-17A levels in P and Ss, CD4+IL-17A+T-cells, in naïve children with mild-moderate asthma/persistent rhinitis after 12 weeks of treatment." (PMID 23573194, 2013). "Additionally, sputum neutrophils were the highest in moderate-severe asthmatics compared with mild asthmatics and IL-17A necessarily led to neutrophilic inflammation in severe asthma." (PMID 22927709, 2012). "IL-17A seems to be involved in the establishment and course of asthma and may offer a new therapeutic target in the treatment of asthma." (PMID 22855687, 2012). "The top pathways enriched for these genes included TNFR2 Signalling, Interferon Signalling, Differential Regulation of Cytokine Production in Intestinal Epithelial Cells by IL-17A and IL-17F, Airway Inflammation in Asthma, Glucocorticoid Receptor Signalling and T Helper Cell Differentiation." (PMID 22701743, 2012). "In addition, Th17 cells and especially their main cytokine IL-17A seem to play a significant role in the pathogenesis of asthma." (PMID 22855687, 2012). "In asthma, IL-17F may play an important regulatory role and seems to function differently than IL-17A." (PMID 21858022, 2011). "In retrospect first hints towards participation of TH17 cells in asthma pathogenesis were reported in 2001 in two studies that detected increased amounts of IL-17 (that is named IL-17A today) in plasma samples and an increased expression of IL-17 mRNA in airway tissues of asthmatic patients." (PMID 20976014, 2010). "Although little is known about the specific role IL-17 plays in asthma, a recent report demonstrated that IL-17R-/- mice displayed reduced IgE production, airway eosinophilia and Th2 cytokine production, suggesting that IL-17A was required for allergic sensitization." (PMID 19060952, 2008). "A significantly higher proportion of patients with moderate-to-severe asthma then with mild asthma had very high levels of IL-8 mRNA (above 50) and/or IL-17A mRNA values (above 50) (IL-8 mRNA: cut-off >50, p = 0.009 and IL-17A mRNA cut-off >50: p = 0.03 by Fisher's exact test respectively)." (PMID 17083726, 2006). "Increased IL-17A mRNA and/or IL-8 mRNA levels could discriminate asthma patients from the healthy control group at a cut-off of 5 for IL-17A mRNA (p = 0.0006 by Fisher's exact test) and at a cut-off of 30 for IL-8 mRNA (p = 0.0009 by Fisher's exact test)." (PMID 17083726, 2006). "In this respect, the presence of elevated IL-26 and/or IL-17 A concentrations in our cohort was not distinctly associated with asthma or specific allergic disease, but rather emerge as general biomarkers of an inflammation that has traditionally been regarded as mediated by Type 2 cytokines." (PMID 38622712, 2024). "Serum concentrations of IL-26 and IL-17 A were measured and compared to subjective and objective demographic characteristics to test our hypothesis, namely that systemic IL-26 and IL-17 A levels are altered in allergen-sensitized children, particularly in those with asthma." (PMID 38622712, 2024). "Furthermore, the asthma group showed increased production of IL-17A and IFN-γ." (PMID 36980265, 2023).
asthma (continued). "Other studies have found that IL-17F, but not IL-17A, underlies airway inflammation in steroid-insensitive toluene diisocyanate-induced asthma models and that anti-IL-17F ameliorates toluene diisocyanate-induced AHR and airway neutrophilia with a reduced Th17 response." (PMID 37377958, 2023). "Moreover, from a clinical perspective, neutrophilic inflammation in asthmatic patients has been observed regardless of steroid therapy as well as in steroid-naïve patients; cytokines frequently involved in T2-low asthma, such as IL-17A and IL-22, are often resistant to steroid action." (PMID 37189844, 2023). "IL-17A seems to play a key role because IL-17A knock-out mice do not experience prolonged hyper-tension, and, on the other hand, this cytokine contributes to airway hyper-responsiveness in mice and is elevated in bronchoalveolar lavage fluid of severe asthma patients." (PMID 36983294, 2023). "Given observed changes in allergen-induced recruitment of IL-17A+ cells in dysbiosis exposed offspring, and the described role of IL-17A-producing cells in driving the development of asthma, we next examined the impact of prenatally induced dysbiosis on the asthma phenotype." (PMID 36032166, 2022). "Decreased IL-17A production may potentially contribute to severe asthma." (PMID 35664352, 2022). "Furthermore, in a mouse model of HDM-induced asthma, gonadectomy in female mice significantly reduced the proportion of IL-13+ and IL-17A+ T cells; in contrast, gonadectomy in male mice significantly increased the proportion of IL-13+ and IL-17A+ T cells." (PMID 35625578, 2022). "Additionally, TH17-secreted IL-17A impacts airway smooth muscle (ASM) remodeling in severe asthma." (PMID 34221020, 2021). "Previous studies examining the expression of IL-17A and IL-17F in asthmatic patients' airways revealed an increase in IL-17A and IL-17F lung immunoreactivity noted in tissues obtained via bronchoscopy and showed increased IL-17A and IL-17F mRNA expression with increased asthma severity." (PMID 34221020, 2021). "Considering the profound role of TLSP, IL-33, and IL-17A signaling in obstructive lung disease pathobiology, we sought to investigate whether the interactions between epithelium and macrophages impact TSLP, IL-33, and IL-17A expression in DCs in asthma and COPD." (PMID 32842623, 2020). "Interestingly, the expression of IL-17A in moDCs was lower in asthma and COPD compared to controls." (PMID 32842623, 2020). "In addition, the results of experiments using transbronchial biopsy samples from patients with severe asthma showed that Th17 cell cytokines, such as IL-17A, IL-17F, and IL-21, are expressed in the airway and that the higher levels of neutrophils were observed." (PMID 32410846, 2020). "Moreover, severity of asthma correlates with the level of IL-17A in the lungs, sputum and BALF." (PMID 30534125, 2018). "Furthermore, AS-IV was found to reduce the IL-17A level in BALF of asthma mice, which might indicate that AS-IV could regulate Th17 dysfunction." (PMID 29234390, 2017). "Hence, we speculate that autoantibody of IL-17A induced in vivo might avoid these weakness and be beneficial to asthma treatment." (PMID 26974537, 2016). "Because increased production of both IL-17A and IFN-γ by CD8-depleted PBMCs was associated with clinical unresponsiveness to glucocorticoid therapy, we compared production of these cytokines in the entire population of asthmatic patients (both SS and SR asthma)." (PMID 25772594, 2015). "Thus, IL-17A has a pivotal role in the pathogenesis of asthma." (PMID 25816135, 2015). "While one study has reported a correlation between IL-17A SNP rs8193036 and paediatric asthma in Taiwanese children, another recent study has provided no such evidence of an association between IL-17A SNP rs8193036 with AR or AR accompanied with asthma in Chinese subjects." (PMID 26196693, 2015). "Furthermore, the Th17 cytokine IL-17A is critical in the pathogenesis of severe asthma." (PMID 25254361, 2014).
asthma (continued). "Th17 cells are distinct population of CD4+ T cells that produce IL-17A, IL-17F and IL-22 and are involved in the pathogenesis of a variety of inflammatory conditions including experimental autoimmune encephalomyelitis, collagen-induced arthritis, psoriasis, allergy and asthma." (PMID 24349168, 2013). "To better understand the role of IL-17A in asthma and rhinitis we investigated: 1) the levels of IL-17A in sputum supernatants (Ss), in nasal wash (NW) and in plasma (P), and 2) the levels of intracellular IL-17A, RORγ(t) and FoxP3 expression in peripheral T-lymphocytes." (PMID 23573194, 2013). "In the pediatric cohort, children with non-T2 asthma displayed a prominent non-T2 inflammatory signature, with significantly higher serum IL-2, IFN-γ, IL-6, and IL-17A compared with T2-high children (p < 0.05 for all indicated comparisons)." (PMID 41601686, 2026). "Children with non-T2 asthma exhibited markedly higher levels of IL-6, IFN-γ, and IL-17A than adults, consistent with a Th1/Th17-dominant immune phenotype." (PMID 41601686, 2026). "Neutrophilic infiltration is driven by increased IFNγ and/or IL‐17A production, and IFNγ and IL‐17A were increased in bronchoalveolar lavage (BAL) fluid and in CD4 and CD8 T cells of patients with severe asthma compared to controls or milder asthma phenotypes." (PMID 41508394, 2026). "Elevated IL-4, IL-9, and TNF-α were observed in non-T2 asthma compared with T2-high asthma, while children exhibited higher levels of IL-2, IL-6, IFN-γ, and IL-17A than adults." (PMID 41601686, 2026). "It is interesting that bacterial sRNAs are predicted to result in the activation of the IL-17A pathway, specifically in RV-only bronchiolitis, indicating that these sRNAs could be involved in changes to the immune system during and after bronchiolitis that may contribute to asthma." (PMID 38410509, 2024). "A study revealed that in an ovalbumin (OVA)-induced asthma model, cDC1-induced CD4+ T cells secreted significantly more IL-4, IL-6, and IL-10, whereas cDC1-induced higher frequencies of IFN-γ and IL-17A production by CD4+ T cells." (PMID 39530090, 2024). "Here, administration of reticuline decreased the production of IL‐17A, MIP‐2, IL‐1β, IL‐5, and RANTES in lung tissues of mice with obesity‐related asthma induced by HDM or OVA." (PMID 38286741, 2024). "Our findings indicate that several cytokines, including IL-5, IL-17A, IL-22, IL-33, TNF-α, leptin, and IL-10 were independently influenced by asthma and obesity." (PMID 39902293, 2024). "Different cytokines were shown to play a key role in driving neutrophilic inflammation in asthma such as CXCL8, IL-17A or TNFα." (PMID 38892358, 2024). "Th17 produces IL-17A and IL-17F, which are elevated in some individuals with asthma and may be responsible for the recruitment of antigen-induced neutrophils into the airways and the enhancement of Th2 cell-mediated eosinophil recruitment into the airways, as seen in steroid-resistant asthma." (PMID 39598135, 2024). "Clinical studies have shown that IL-17A is significantly increased in bronchoalveolar lavage fluid (BALF) and serum of asthma patients compared to healthy people." (PMID 38579176, 2024). "Thus, given that IL-17A and IL-25, which both use, in part, IL-17RA to exert their biological effects, are significantly greater in sputum of obese as compared to non-obese asthmatics, future studies focusing on the effectiveness of brodalumab in obese asthma is warranted." (PMID 38878250, 2024). "In our study, we observed that the salubrinal administration (DUSP2 inhibitor) reversed neutrophilic airway inflammation and cytokine responses (IL-17A, TNF-α) in a steroid-resistant asthma mouse model." (PMID 37208441, 2023). "In our asthma mouse model sensitized with OVA, the lung tissues were significantly damaged and the contents of inflammatory cytokines (IL-17A and IL-6) were considerably increased, while the content of IL-10 was significantly decreased." (PMID 36743692, 2023).
asthma (continued). "Therefore, it is interesting to speculate that in humans with TH2-mediated asthma, additional stimuli leading to IL-17A production also lead to increased neutrophil inflammation through increased IL-8 production due to increased expression of the IL-17 receptor." (PMID 37443808, 2023). "Particularly, the inflammatory milieu of asthma exacerbation has arisen as an inducer of the NET mechanism, whereas IL-17A, which is expressed on NET structures, promotes collagen production by lung fibroblasts." (PMID 37626601, 2023). "Therefore, it could be deduced that TSLP and IL-17A are involved in asthma development." (PMID 36834541, 2023). "CircSORT1 expression correlated with various asthma clinical parameters, including FeNO, EOS%, IL-17A, IFN-γ, and PC20." (PMID 38078005, 2023). "Ourteam also reported an increase in the levels of IL-17A cytokines and a decrease in the levels of IL-10 in BALF, and the Th17/Treg imbalance is an important mechanism in asthma development." (PMID 37485534, 2023). "Our results have confirmed that patients with asthma and obesity have increased levels of circulating inflammatory cytokines such as TNF-α, IL-2, IL-4, and IL-17a despite the basic anti-inflammatory therapy." (PMID 37367676, 2023). "As rBmTI-A reduced the concentrations of IL-5, IL-10, IL-13, and IL-17A, CrataBL reduced the numbers of IFN-γ, IL-4, IL-5, IL-13, and IL-17 positive cells in the airways and alveolar walls; both studies used an asthma model." (PMID 37511021, 2023). "Aside from Th2 cells, Th17 cells and the IL-17A they produce are the most frequently observed and studied CD4 T cell populations in asthma." (PMID 37163370, 2023). "In this model, inhibition of Th17 cell differentiation and, thus, reduction of IL-17A release significantly lowered infiltration of neutrophils into the airways and pathological hallmarks of HDM-induced experimental asthma." (PMID 35883573, 2022). "We isolated T cell from 16 clinical samples, including 6 normal controls and 10 severe asthma patients, and then measured the expression level of STAT4-AS1 and IL-17A." (PMID 35528611, 2022). "AYC-EV (8 mg/kg)-treated asthma-induced mice (G4) showed decreased levels of IFN-γ+CD4+, IL-5+CD4+, IL-17A+CD4+, and IL-5+IL-17A+CD4+ T cells as compared to the disease-causing groups (G2)." (PMID 36139376, 2022). "Several stimuli, such as pathogens, allergens, and cigarette smoke, as well as cytokines (IFN-γ, IL-17A, IL33, TSLP, TNFα, TGFβ) have been shown to promote corticosteroid insensitivity in severe asthma and COPD13." (PMID 35773318, 2022). "Linggan Wuwei Jiangxin formula (LGWWJX) can protect against obese asthma most likely through mechanisms, including the inhibition of the IL-1β/ILC3/IL-17A/AHR axis and the regulation of lipid metabolism." (PMID 36051916, 2022). "IL-17A is known to induce goblet cell hyperplasia and mucus production, which are prominent features of airway diseases, such as COPD, asthma, and cystic fibrosis." (PMID 35773318, 2022). "TNF-α, IL-13, IL-4, IL-17A and CCL2 are found to increase RhoA mRNA expression via NF-κβ and STAT6 signaling pathways activation, leading to airway hyperreactivity in asthma." (PMID 34069141, 2021). "Intriguingly, TLR-6 upregulated during A. fumigatus exposure contributes to IL-17A and IL-23 production by TH17 cells in response to fungal allergens during asthma." (PMID 33921169, 2021). "Compared to the asthma and COPD groups, higher levels of IL-4, IL-6, TNF-α, IL-1β, IL-17A, and IFN-γ in ACO were observed, and there were significances in IL-4, IL-6, TNF-α, and IFN-γ compared to the control group (P < 0.01)." (PMID 33869177, 2021). "IL-17A and IL-17F are both involved in the pathogenesis of neutrophilic inflammation observed in COPD and severe asthma." (PMID 34075087, 2021).
asthma (continued). "We discovered higher STAT3 expression and lower SOCS3 expression in the lung tissue of asthma patients compared with that of healthy controls (HCs) and observed a correlation between STAT3 expression or SOCS3 expression and the expression of IL-17A protein." (PMID 34760922, 2021). "The levels of IL-6 and MCP-1 in the asthma group were significantly higher than those in the healthy control group (IL-6: P = 0.013, MCP-1: P = 0.003), while IL-17A showed an opposite trend (P < 0.001)." (PMID 32295589, 2020). "Th1 and Th17- type responses have also been shown to play a role in asthma pathogenesis, and elevated levels of IFN-γ, TNF-α, and IL-17A can be found in the serum of asthmatic patients." (PMID 32194407, 2020). "In the present study, we found a link (involving IL-17A, MMP-1, and MMP-9 expression) between cigarette smoke and neo-osteogenesis in AE with asthma and CRS." (PMID 31653934, 2019). "Intratracheal administration of S. commune in OVA-induced asthma model mice enhanced neutrophilic airway inflammation, increased the mRNA expression of CXCL1 and CXCL2 in the lungs, and provoked IL-17A, and IL-17F production in BAL fluid." (PMID 31852931, 2019). "The present is the first study to evaluate the link between cigarette smoke and AE neo-osteogenesis in patients with asthma and CRS in terms of IL-17A and MMP expression." (PMID 31653934, 2019). "Increased expression of IL-17A has been documented in the lungs, sputum, BALF, and serum of patients with asthma." (PMID 30233389, 2018). "Increased serum IL17A and IL33 levels were found in patients with various degrees of asthma as well as steroid-resistant and neutrophilic asthma." (PMID 30306094, 2018). "The adjusted ORs (95%CI) of abnormal expressions of elevated IL-17A, decreased adipsin and CCL11 for adult asthma patients were 12.50 (5.52, 28.34), 19.55 (11.74, 32.55), and 4.13 (1.78, 9.55) in comparison with normal level, respectively." (PMID 29138487, 2017). "Serum IFN-γ, IL-4, and IL-17A levels were increased in RSV and asthma mice compared with control mice while IL-10 levels were decreased." (PMID 29123203, 2017). "Concurrently, levels of IFN-γ, IL-4, and IL-17A in serum, lung tissues, and BALF increased in RSV-infected asthma mice while levels of IL-10 declined." (PMID 29123203, 2017). "Both proportion and cell counts of CD4+IL-17A+ cells increased and CD4+Foxp3+ cells decreased in asthma model." (PMID 26612993, 2015). "The data presented in this article demonstrate that there is a significantly higher production of IL-17A and IFN-γ in PBMC cultures from patients with SR asthma compared with those from patients with SS asthma." (PMID 25772594, 2015). "We tested the expression of IL-17A, RORγ(t) and FOXP3 in peripheral blood T-lymphocytes from intermittent and mild-moderate asthma." (PMID 23573194, 2013). "Therefore, it can be speculated that targeting IL-17A is promising in asthma treatment." (PMID 22855687, 2012). "The cytokine concentrations of IL-17A were assayed in 28 sporadic and 4 familial ALS patients, 10 normal control subjects, and 4 subjects suffering from episodes of eczema or asthma." (PMID 21062492, 2010). "In the pediatric cohort, non-T2 asthma was characterized by higher circulating IL-2, IFN-γ, IL-6, and IL-17A compared with T2-high disease, whereas these same Th1/Th17-associated and pro-inflammatory cytokines were uniformly low and non-discriminatory in adults." (PMID 41601686, 2026). "Our cytokine analysis revealed that pediatric non-T2 asthma is characterized by elevated Th1 and Th17 cytokines, including IL-2, IL-6, IFN-γ, and IL-17A, accompanied by the downregulation of immunoglobulin-associated genes, indicating an attenuated Th2 signature and reduced atopy." (PMID 41601686, 2026). "Additionally, we explored the correlations between the microbial profiles and inflammatory cytokines known to play key roles in asthma pathogenesis, including IFN-γ, IL-4, IL-5, IL-13, IL-17A, IL-10, and TGF-β1." (PMID 40871265, 2025).